AFP (alpha fetoprotein)
Diseases named in the same sentence as AFP in open-access papers (continued):
Sharing a sentence is not in itself a finding about the gene and the disease.
liver cancer (continued). "However, at the time of clinical diagnosis of liver cancer, the staging of AFP-negative HCC was tantamount to that in AFP-positive HCC patients, which may be related to the lack of extensive use of a highly sensitive screening index." (PMID 23981851, 2013). "Real-world Applications of quantum dots are identified as an optimal surface coating for quantum dots to minimize nonspecific binding and enhance the targeting of alpha-fetoprotein (AFP), a common liver cancer biomarker." (PMID 39841330, 2025). "On the other hand, lower liver cancer cases could be due to non-documentation in the Pathology departments because most hepatologists presently avoid liver biopsy, rather relying on clinical features, serum alpha-fetoprotein levels and radiological imaging for diagnosis." (PMID 39087021, 2024). "Propensity score (PS) matching was used to compare TCM users (n = 485) with non-users (n = 485) in terms of age, Barcelona Clinic Liver Cancer (BCLC) staging, type of treatment, and AFP." (PMID 38464727, 2024). "There is an urgent need to explore new strategies for the identification of high-risk groups for liver cancer and for the screening of HCC patients, especially those with early-stage HCC, AFP-negative HCC, and micro-liver cancer in the subclinical stage." (PMID 37189543, 2023). "Serum alpha-fetoprotein (AFP) assay is a traditional useful method for diagnosis and monitoring of HCC, but the application of AFP for liver cancer is unsatisfactory, and it is not sufficient to predict the prognosis for HCC patients effectively." (PMID 36507118, 2022). "AFP-positive liver cancer cells were also more sensitive to the PIAF and L-OHP + EPI regimens than AFP-negative cells." (PMID 35127582, 2022). "Another study found that fibrinogen to pre-albumin ratio was gradually increased alongside with the development of AFP-negative HCC and positively correlated with tumor size and Barcelona Clinic Liver Cancer stages (BCLC)." (PMID 35461226, 2022). "A high alpha-fetoprotein level, high carbohydrate antigen 19-9 (CA19-9) level, advanced Barcelona Clinic Liver Cancer (BCLC) stage, and lack of tumor encapsulation were found to be associated with worse OS and RFS using univariate analysis." (PMID 33893729, 2021). "Compared to other subtypes of liver cancers, for SHC, neither the clinical symptoms nor the medical examination results, such as AFP levels, Child-Pugh classification, tumor-node-metastasis stage, and medical imaging, can specifically differentiate SHC." (PMID 32733821, 2020). "ALBI, Albumin-Bilirubin; AFP, α-fetoprotein; AJCC, American Joint Committee on Cancer; BCLC, Barcelona Clinic Liver Cancer; a)Partial data was not available." (PMID 31611609, 2019). "The IHC experiments indicated that the liver cancer tissues induced by pT3-TRIM71 alone did not express Ck7 and Ck19, and β-catenin was primarily localized in the cytoplasmic matrix, with tumors expressing AfP and Arg1." (PMID 39267787, 2024). "Alpha-fetoprotein (AFP), although recognized as a reliable marker for liver cancer screening and early diagnosis, numerous studies have shown that nearly 80% of small HCC nodules do not exhibit elevated AFP levels, and its sensitivity for tumors smaller than 3 cm is less than 25%31." (PMID 38802416, 2024). "Unfortunately, our results could highlight the importance of serum TERT C228T for the detection of non-viral FLD-related liver cancer, but the superiority of TERT C228T could not be compared with AFP or with PIVKAII." (PMID 35306637, 2022). "However, the efficacy of the combination of AFP + MDK, GPC3 + OPN has not been determined yet; therefore, significance of the combined use of these tumor markers in the diagnosis of liver cancer should be investigated in the near future." (PMID 34513063, 2021). "In liver cancer cells (HepG2), they more like employ CD36, and a lesser degree the LOX-1, SRB1 and SREC-1 scavenger receptors rather than mannose receptor for uptake of AFP." (PMID 33718192, 2021).
liver cancer (continued). "Thus, we hypothesize that serum biomarkers would vary between AFP-positive and negative HCC patients and could be indicators of liver cancer pathogenesis and possibly useful in clinical management and prognostication." (PMID 35461226, 2022). "Furthermore, among the 37 cases of AFP negative sera (37%), 23 cases (62%) were VASN positive (≥ 1.5061ng/ml), which suggested that combining the use of AFP and VASN could improve the sensitivity of liver cancer diagnosis." (PMID 25826090, 2015).
liver cirrhosis (528 papers, 2004 to 2026). "Our study aims to investigate the miRNA-101 differential expression in Egyptian HCV-induced HCC patients’ serum versus HCV liver cirrhosis (LC) as prospective diagnostic biomarkers compared to alpha-fetoprotein (AFP)." (PMID 39753619, 2025). "Key OS risk factors include liver cirrhosis, portal hypertension, AFP levels > 20 ng/mL, tumor diameter > 3 cm, multiple and subcapsular tumors, frequent recurrence, and early recurrence." (PMID 40958046, 2025). "HCC predominantly affects males, is often associated with a history of hepatitis B or C and liver cirrhosis, and typically shows elevated AFP levels." (PMID 40860825, 2025). "The univariable analysis identified that liver cirrhosis, treatment modalities, tumor number, and AFP level were risk factors for re-recurrence of HCC (all P < 0.05)." (PMID 38773564, 2024). "In a study of urothelial cell carcinoma, the rs1966265 variant was associated with tumor progression and histologic grade, and the rs351855 variant was associated with liver cirrhosis and increased AFP levels in hepatocarcinoma." (PMID 38540215, 2024). "Further, it was found that DNAH17 methylation was associated with gender, age, serum AFP values, liver cirrhosis, tumor fibrous capsule, tumor necrosis, and tumor thrombus." (PMID 38724875, 2024). "Clinicopathological features, including TNM stage, depth of tumor invasion, lymph node metastases, tumor size, AFP level, and liver cirrhosis, were analyzed for associations with CTC-WBCs." (PMID 38087278, 2023). "According to some studies, male, blood transfusion, liver cirrhosis, larger tumor size than 5 cm, microvascular invasion, high serum alpha-fetoprotein, and satellite lesions are associated with worse outcomes." (PMID 36717904, 2023). "The identification of serum AFP cannot distinguish between increased AFP caused by other factors such as liver cirrhosis, or chronic hepatitis caused by HBV or HCV infection." (PMID 35699406, 2022). "Based on the risk model, a larger proportion of patients with high serum AFP, Child-Pugh class B/C, liver cirrhosis, and advanced tumor stage were defined as high-risk." (PMID 35141283, 2022). "In this study, we also found that HBV infection was associated with 5-year earlier onset and higher AFP, liver cirrhosis, advanced BCLC stage, and vascular tumor thrombus in ICC." (PMID 35800051, 2022). "Univariate analyses demonstrated significant associations between serum AFP, liver cirrhosis, ALBI stage, tumor size, microvascular invasion and DAA treatment with RFS." (PMID 35208582, 2022). "In this sense, screening every 6–12 months with ultrasound associated with alpha-fetoprotein dosage is recommended in patients with chronic hepatitis B, especially in those with liver cirrhosis." (PMID 35458462, 2022). "Other covariates including tumor number, tumor diameter, liver cirrhosis, AFP level, ALT level, and GGT level were also associated with TTR (P < .05 for each covariate)." (PMID 32702202, 2020). "Some preoperative variables, such as tumor number, tumor differentiation, tumor size, alpha-fetoprotein (AFP) level, liver function, and the presence of liver cirrhosis have been associated with OS of HCC patients after hepatectomy." (PMID 33505912, 2020). "CRC, liver cirrhosis, elevated AFP level, and thrombocytopenia independently predict the risk for HCC in patients with ALD." (PMID 30824851, 2019). "Clinicopathological analysis showed that Rab27a expression was linked with elevated serum AFP (P = 0.009), vascular invasion (P = 0.031) and liver cirrhosis (P = 0.035)." (PMID 29725020, 2018). "Statistical analysis indicated that high MCM6 expression was associated with hepatitis B infection, liver cirrhosis, multiple tumor nodules, high serum AFP and early recurrence." (PMID 29357919, 2018).
liver cirrhosis (continued). "In the present study, we demonstrated that a high expression of the EMT inducer, FOXC2, in primary HCC samples is associated with liver cirrhosis, malignant potential, high serum AFP, and poor prognosis." (PMID 29801468, 2018). "At the same time, AFP ≥ 400 ng/mL, multiple tumors, macroscopic vascular invasion, and liver cirrhosis were also statistically associated with poor RFS." (PMID 28572700, 2017). "Other significant associated factors included etiology, liver cirrhosis, Child-Pugh stage, hemoglobin, AFP, and modified UICC stage." (PMID 27468402, 2016). "We observed that genetic polymorphism in FGFR4 rs351855 (Gly/Arg and Arg/Arg) was associated with high risk (OR: 2.113, 95% CI: 1.188–3.831) of liver cirrhosis and markedly increased the AFP level in patients with HCC." (PMID 25860955, 2015). "Few studies have been conducted to evaluate liver cirrhosis by analyzing AFP levels or evaluating associations between AFP levels and fibrosis stages." (PMID 25128299, 2014). "Factors not significantly affecting overall survival included age, gender, HBV infection, AFP level, underlying liver cirrhosis, Child-pugh classification, tumor encapsulation and tumor differentiation." (PMID 22747650, 2012). "Liver cirrhosis itself could lead to liver cell regeneration and inflammatory activity, thereby causing a mild increase in AFP." (PMID 40936688, 2025). "Furthermore, univariate Cox regression analysis identified tumor size, TNM stage, serum AFP levels, liver cirrhosis, and high CENPB protein expression as risk factors influencing OS and RFS." (PMID 37925172, 2023). "Although various studies have deepened our understanding of HCC carcinogenesis, HCC surveillance mainly relies on abdominal ultrasonography and blood alpha-fetoprotein (AFP) measurements in high-risk groups with hepatitis B, hepatitis C, and liver cirrhosis (LC)." (PMID 37899451, 2023). "In addition, the ROC comparative analysis of liver cirrhosis also showed superior diagnostic results compared to AFP." (PMID 35456219, 2022). "Notably, CHC patients were associated with a high incidence of underlying liver cirrhosis and elevated AFP level in comparison with ICC patients, which was in accordance with previous findings." (PMID 34862762, 2022). "The combination of zonulin and AFP exhibited a significantly larger receiver operating characteristic curve compared to zonulin or AFP alone, suggesting that their combination confers significant benefit to diagnostic accuracy in differentiating liver cirrhosis from HCC." (PMID 34957088, 2021). "Importantly, we found that DNAH17 methylation was associated with gender, age, serum AFP values, liver cirrhosis, tumor fibrous capsule, tumor necrosis, and tumor thrombus." (PMID 30575322, 2019). "In addition, HOXC6 overexpression was positively associated with high AFP level, liver cirrhosis, larger tumor, vascular invasion and BCLC stage." (PMID 29348394, 2018). "Our findings suggest that genetic polymorphism in FGFR4 rs351855 may be associated with the risk of HCC coupled with liver cirrhosis and may markedly increase the AFP level in Taiwanese patients with HCC." (PMID 25860955, 2015). "First, AFP elevation may be associated with chronic liver diseases such as viral hepatitis and liver cirrhosis as well as HCC." (PMID 26252472, 2015). "In addition, although miR-148a (AUC of 0.860) alone was significantly superior to AFP (AUC of 0.665), the combination of miR-122, miR-148a, and AFP exhibited a higher diagnostic power in discriminating early HCC from liver cirrhosis in humans, with an AUC of 0.947." (PMID 32443747, 2020). "Moreover, AFP was only associated with OS, and liver cirrhosis was only associated with TTR." (PMID 24716838, 2014). "Most AEs were mild in intensity; SAEs (significant increase in ALT activity, HCC dissemination, liver cirrhosis decompensation in two patients, increase in alpha-fetoprotein concentration) were reported in five patients." (PMID 41517592, 2026).
liver cirrhosis (continued). "The collected clinical data included age, gender, HBV infection, liver cirrhosis, AFP levels, and more." (PMID 40730604, 2025). "Thirteen independent prognostic factors with non-zero coefficients were identified: age, BMI, Child-Pugh grade, liver cirrhosis, AFP, FIB, Hb, LDH, PDW, PNI, SII, HALP and APRI." (PMID 41403946, 2025). "This study also identified liver cirrhosis, portal hypertension, AFP > 20 ng/mL, tumor diameter > 3 cm, multiple tumors, and subcapsular location as independent predictors for poor OS, which aligns with prior reports." (PMID 40958046, 2025). "The HCC surveillance guidelines included recommendations for routine HCC surveillance via 6-monthly ultrasound (US) imaging for people with compensated liver cirrhosis, with the potential addition of alpha-fetoprotein (AFP) blood testing." (PMID 40584144, 2025). "Multivariate Cox analysis indicated that age, AFP, liver cirrhosis, tumor capsule, lymphatic metastasis, tumor differentiation, and the expression of CK19, Ki67, and β-catenin were independent prognostic factors." (PMID 41388520, 2025). "Conversely, those with MAFLD showed significantly shorter prothrombin time and lower prevalence of alpha-fetoprotein > 400 ng/ml, liver cirrhosis, Child-Pugh grade B, multinodular tumors and current smoker." (PMID 38693556, 2024). "The main risk factors for postoperative recurrence include microvascular invasion of the primary tumor, liver cirrhosis, high AFP levels, and larger tumor volume." (PMID 38567153, 2024). "Patients with older age (>65 years), HBV or HCV infection, liver cirrhosis, higher AFP level (>20 ng/mL), or larger tumor size (>5 cm) had shorter survival (p < 0.01)." (PMID 39796655, 2024). "The aim of our study was to evaluate the diagnostic accuracy of serum AFP and PIVKA‐II or their combination in HCC diagnosis among Caucasian patients with compensated or decompensated liver cirrhosis of various etiologies." (PMID 38361401, 2024). "The majority of patients (93%) had liver cirrhosis in stages 1–2, and more than half of the patients (59%) had AFP levels <400 ng/ml." (PMID 39132868, 2024). "SLC7A11 levels were also shown to be a complementary marker for alpha fetoprotein (AFP) levels in the diagnosis of HCC from liver cirrhosis." (PMID 39335604, 2024). "The assessed patient clinicopathological characteristics included sex, age, HBsAg, serum AFP, liver cirrhosis, TNM, Child-Pugh class, tumor size, tumor differentiation and vascular invasion." (PMID 38500533, 2024). "The patient's medical history, including a prior infection with hepatitis B virus, cirrhosis of the liver and an alpha-fetoprotein (AFP) level measuring 41.28 ng/ml substantiated the clinical diagnosis of HCC." (PMID 38380371, 2024). "They found that EV miRNA-148a had an AUROC of 0.891 (95% CI: 0.809–0.947) for differentiating HCC from liver cirrhosis, while AFP had an AUROC of 0.712 (95% CI: 0.607–0.803)." (PMID 39451600, 2024). "The five included studies reported demographic data of all patients or patients with liver cirrhosis, including age, sex, hemoglobin, total bilirubin (TB), albumin, and alpha-fetoprotein (AFP), and they were extremely comparable." (PMID 39398946, 2024). "Age, liver cirrhosis, tumor number, tumor size, AFP level, tumor differentiation grade, TNM stage, and KLF4 expression were all significantly associated with OS and RFS in the univariate analysis." (PMID 36936440, 2023). "Prognostic factors such as tumor size, microvascular invasion, liver cirrhosis, alpha-fetoprotein (AFP) levels, and the viral replication status of HBV influence HCC prognosis, with viral load being the most clinically manageable." (PMID 38042834, 2023). "The models were trained with features extracted from CEUS examinations, clinical data such as the presence of underlying liver disease (HBV infection, chronic hepatitis C, liver steatosis and liver cirrhosis) and laboratory data (alpha-fetoprotein level)." (PMID 37958282, 2023).